NT5DC3 (5'-nucleotidase domain containing 3)
Synonyms: TU12B1-TY; FLJ11266; TU12B1TY
Tractability: PROTAC: ubiquitination databases record sites on it; its protein half-life has been measured.
Gene: Protein-coding gene on chromosome 12 (103,770,453 to 103,841,260, reverse strand). Ensembl gene ENSG00000111696.
Subcellular location (Human Protein Atlas): Mitochondria; Cytosol
Gene Ontology:
Molecular function: phosphatase activity
Cellular component: mitochondrion; receptor complex; cytosol
Genetic constraint (gnomAD): Loss-of-function variants: 19 observed, 39.29 expected, observed/expected ratio (o/e) 0.48, 90% interval 0.34 to 0.71. The upper end of that interval is the gene's LOEUF score, 0.71, which puts it in group 2 of 6, group 1 being the genes least tolerant of losing a copy. Missense variants: 389 observed, 483.27 expected, observed/expected ratio (o/e) 0.8, 90% interval 0.74 to 0.88. Synonymous variants: 177 observed, 181.7 expected, observed/expected ratio (o/e) 0.97, 90% interval 0.86 to 1.1.
Homologues: Orthologues: chimpanzee NT5DC3 (100% identical), rat Nt5dc3 (92% identical), mouse Nt5dc3 (92% identical), pig NT5DC3 (86% identical), dog NT5DC3 (85% identical), guinea pig NT5DC3 (85% identical), tropical clawed frog nt5dc3 (76% identical), zebrafish nt5dc3 (71% identical), rabbit NT5DC3 (69% identical), Drosophila melanogaster Nt5c (42% identical), Drosophila melanogaster Nt5b (26% identical), Caenorhabditis elegans Y71H10B.1 (24% identical). Paralogues in human: NT5DC2 (60% identical), NT5C2 (26% identical), NT5DC4 (21% identical), NT5DC1 (20% identical).
Diseases named in the same sentence as NT5DC3 in open-access papers:
NT5DC3 is named in the same sentence as 16 diseases in open-access papers, as found by Europe PMC text mining. Sharing a sentence is not in itself a finding about the gene and the disease. The quoted sentences say what the papers report.
colon cancer (3 papers, 2022 to 2023). "If possible, the measurement of NT5DC3 expression level might be developed as a sensitive biomarker in clinical prediction models, to distinguish whether T2D patients are susceptible to developing colon cancer." (PMID 36855062, 2023). "As the LF-dependent NT5DC3/HKDC1 expression alteration in colon cancer, we sought to determine the relevance of LF and downstream targets NT5DC3/HKDC1 in HT29 tumor model in vivo." (PMID 36855062, 2023). "Excitingly, the following epigenetic assessments in the present study further accounted for the dys-expression of NT5DC3 and its key role in the progression of colon cancer under hyperglycemia." (PMID 36855062, 2023). "On the other hand, based on the co-analysis of transcriptomics and DNA methylation detection, we defined NT5DC3 as the tumor suppressor in inhibiting colon cancer and preliminarily identified the regulation of LF on NT5DC3." (PMID 36855062, 2023). "Our study reveals that lactoferrin and its downstream target NT5DC3 represent a new light in clinical T2D-induced colon cancer prognosis and treatment, underscoring the potential application of natural dietary mediated tumor suppression." (PMID 36855062, 2023). "Strikingly, clinical blood samples analysis demonstrates NT5DC3 protein expression is required to direct the distinction of T2D or T2D-induced colon cancer with healthy humans." (PMID 36855062, 2023). "In conclusion, the present study verified the inhibitory effect of LF in the development of T2D colon tumors by regulating Thr6/Ser11 phosphorylation in the NT5DC3 protein and its downstream factors." (PMID 36553697, 2022). "Moreover, co-treatment of lactoferrin and NT5DC3 protein restrains the growth of colon tumors by altering the aberrant epigenetic markers." (PMID 36855062, 2023). "NT5DC3 has been previously reported to be altered in colon cancer." (PMID 36855062, 2023). "In this study, we found NT5DC3 as a key target of diabetes and colon cancer under hyperglycemia." (PMID 36855062, 2023). "These discoveries about the mechanism of NT5DC3 in suppressing colon cancer progression under hyperglycemia, combined with the positive regulation of LF on NT5DC3, will expand current knowledge of the functions of bioactive proteins within different research layers." (PMID 36855062, 2023). "This study reveals the underlying mechanism by which LF-dependent DNA 5mC and RNA m6A remodeling in epigenetically regulating the NT5DC3/HKDC1 axis, and subsequently inhibiting colon cancer progression under hyperglycemia." (PMID 36855062, 2023). "Our study uncovered that WTAP participated in m6A (2309) of NT5DC3 to suppress NT5DC3 expression thus, LF-dependent WTAP expression inhibition exhibited a novel pathway to suppress the progression of colon tumor under a high concentration of glucose." (PMID 36855062, 2023). "In brief, we revealed that lactoferrin acts as a suppressor in the progression of colon cancer under a high concentration of glucose, by which epigenetically regulating glucose-dependent DNMT/5mC or WTAP/m6A/NT5DC3/HKDC1 axis." (PMID 36855062, 2023). "Further investigation should be conducted to ascertain whether this mechanism holds true in more clinical T2D-induced colon tumor patients, or whether LF inhibits the progression of the two diseases via acting on WTAP/m6A/NT5DC3/HKDC1 axis in the clinical area." (PMID 36855062, 2023). "Moreover, LF-dependent up-regulating of NT5DC3 and down-regulating of HKDC1 expression provided strong evidence that NT5DC3 and HKDC1 might play pivotal roles in the induction of T2D to colon tumor which could be relieved by LF." (PMID 36855062, 2023).
colorectal cancer (2 papers, 2022 to 2023). A primary or metastatic malignant neoplasm that affects the colon or rectum. "Since reports involving the role of NT5DC3 in colorectal cancer are rare, it is necessary to examine it as a key risk factor." (PMID 36553697, 2022).
Hyperglycemia (2 papers, 2022 to 2023). An increased concentration of glucose in the blood. "The expression of NT5DC3 declined significantly during hyperglycemia, while that of other proteins, such as p-PI3K, p-AKT, p-mTOR, IL-1β, and TNF-α, was substantially higher." (PMID 36553697, 2022). "The results indicated that NT5DC3 efficiently suppressed the development of T2D to colorectal tumors in BALB/c mice, while NT5DC3 protein expression declined during hyperglycemia, and LF inhibited this malignant progression by regulating the levels of NT5DC3 and the PI3K/AKT/mTOR signaling pathways." (PMID 36553697, 2022).
breast carcinoma (1 paper, 2023). "There was a downregulation of NT5C2, NT5DC1, and NT5DC3 in breast cancer compared to normal tissues, and NT5DC2 instead." (PMID 36820551, 2023). "The results of the TIMER database showed that the expression of NT5C2, NT5DC1, and NT5DC3 were significantly downregulated in breast cancer tissues, while the expression of NT5DC2 were upregulated." (PMID 36820551, 2023). "According to our study, the expression of NT5C2, NT5DC1, and NT5DC3 was downregulated, while the expression of NT5DC2 was upregulated in breast cancer tissues." (PMID 36820551, 2023).
colorectal tumors (1 paper, 2022). "The present study examined the role of NT5DC3 in colorectal tumor growth." (PMID 36553697, 2022).
intrahepatic cholangiocarcinoma (1 paper, 2025). A carcinoma that arises from the intrahepatic bile duct epithelium in any site of the intrahepatic biliary tree. "Univariate logit binomial analysis, with the outcome being the proliferative subclass status of intrahepatic cholangiocarcinoma, confirmed the significance of the probes for seven enzymes: FH, MAT2B, PLOD2, PLOD1, PDE6D, ALDOC, and NT5DC3." (PMID 40034261, 2025). "Based on the training and validation cohorts of intrahepatic cholangiocarcinoma (ICA) bulk transcriptomes, seven metabolic enzymes were confirmed to be overexpressed in cases with poor prognosis: FH, MAT2B, PLOD2, PLOD1, PDE6D, ALDOC, and NT5DC3." (PMID 40034261, 2025).
tumor (6 papers, 2017 to 2025). "Furthermore, we observed that co-treatment of LF could neutralize the differential expression of NT5DC3 and HKDC1 induced by glucose concentration (comparing with control, P < 0.05), suggesting the important mechanism underlying LF’s anti-tumor activity via the regulation of NT5DC3 and HKDC1." (PMID 36855062, 2023). "NT5DC1 expression correlated with patient sex, NT5DC3 expression was significantly associated with cancer grade, and NT5DC4 expression was associated with tumor diameter." (PMID 37576396, 2023). "We observed that the expression of NT5C2 (P=0.0055), NT5DC2 (P=0.027), and NT5DC3 (P=0.035) was closely correlated with tumor stage, suggesting that the expression of NT5C2, NT5DC2, and NT5DC3 increased significantly with the progression of HCC." (PMID 35047040, 2022). "Many studies showed that NT5C2, NT5DC2, and NT5DC3 played an important role in tumor development." (PMID 35047040, 2022). "To this end, we assessed the HT29 implantation tumor model in immune-competent C57BL/6 mouse by LF, NT5DC3 protein, or HKDC1 antibody or combination treatment both in normal and diabetic mice." (PMID 36855062, 2023). "We observed single LF, NT5DC3 protein, or HKDC1 antibody treatment could partially suppress the tumor growth." (PMID 36855062, 2023).
NT5DC3 also shares sentences with these, for which no sentence is quoted: cancer (4 papers); acute leukemia (1); astrocytoma (1); diabetes (1); glioblastoma (1); hepatocellular carcinoma (1); leiomyosarcoma (1); lung carcinoma (1); type 2 diabetes (1).